PTPRK (protein tyrosine phosphatase receptor type K)
Description:
Regulation of processes involving cell contact and adhesion such as growth control, tumor invasion, and metastasis. Negative regulator of EGFR signaling pathway. Forms complexes with beta-catenin and gamma-catenin/plakoglobin. Beta-catenin may be a substrate for the catalytic activity of PTPRK/PTP-kappa.
Synonyms: R-PTP-kappa
Tractability: Small molecule: it has a binding pocket of medium quality. Antibody: its Gene Ontology location is reachable by antibodies, with high confidence; UniProt places it where antibodies can reach, with medium confidence; UniProt predicts a signal peptide or a membrane-spanning region; the Human Protein Atlas places it where antibodies can reach. PROTAC: ubiquitination databases record sites on it; its protein half-life has been measured.
Gene: Protein-coding gene on chromosome 6 (127,968,780 to 128,520,619, reverse strand). Ensembl gene ENSG00000152894.
Subcellular location: Cell junction, adherens junction; Cell membrane
Subcellular location (Human Protein Atlas): Cell Junctions; Connecting piece; Flagellar centriole; Plasma membrane; Vesicles
Pathways (Reactome):
Signal Transduction: EGFR downregulation
Gene Ontology:
Molecular function: beta-catenin binding; gamma-catenin binding; protein binding; protein kinase binding; protein tyrosine phosphatase activity; transmembrane receptor protein tyrosine phosphatase activity
Biological process: cell adhesion; cell migration; cellular response to reactive oxygen species; cellular response to UV; focal adhesion assembly; negative regulation of cell cycle; negative regulation of cell migration; negative regulation of cell population proliferation; negative regulation of DNA-templated transcription; negative regulation of keratinocyte proliferation; protein dephosphorylation; protein localization to cell surface; signal transduction; transforming growth factor beta receptor signaling pathway; neuron projection development
Cellular component: cell junction; cell surface; cell-cell junction; leading edge membrane; plasma membrane; membrane; adherens junction
Genetic constraint (gnomAD): Loss-of-function variants: 64 observed, 154.54 expected, observed/expected ratio (o/e) 0.41, 90% interval 0.34 to 0.51. The upper end of that interval is the gene's LOEUF score, 0.51, which puts it in group 2 of 6, group 1 being the genes least tolerant of losing a copy. Missense variants: 1,326 observed, 1,711.1 expected, observed/expected ratio (o/e) 0.77, 90% interval 0.74 to 0.81. Synonymous variants: 588 observed, 591.18 expected, observed/expected ratio (o/e) 0.99, 90% interval 0.93 to 1.07.
Homologues: Orthologues: chimpanzee PTPRK (99% identical), macaque PTPRK (99% identical), rabbit PTPRK (99% identical), dog PTPRK (99% identical), mouse Ptprk (99% identical), rat Ptprk (98% identical), guinea pig PTPRK (98% identical), pig PTPRK (97% identical), tropical clawed frog ptprk (92% identical), zebrafish ptprk (69% identical). Paralogues in human: PTPRM (62% identical), PTPRU (59% identical), PTPRT (58% identical), PTPRD (30% identical), PTPRF (30% identical), PTPRS (30% identical), PTPRZ1 (23% identical), PTPRG (21% identical), PTPRC (19% identical), PTPRB (18% identical), PTPRA (18% identical), PTPRE (17% identical), and 23 more.
Diseases named in the same sentence as PTPRK in open-access papers:
PTPRK is named in the same sentence as 51 diseases in open-access papers, as found by Europe PMC text mining. Sharing a sentence is not in itself a finding about the gene and the disease. The quoted sentences say what the papers report.
breast carcinoma (9 papers, 2017 to 2025). "Reduced expression of Protein Tyrosine Phosphatase Receptor Type K was associated with poor prognosis in breast cancer and decreased activity of PTPRK with less resistant phenotype in gliomas." (PMID 33921897, 2021). "Specifically, the downregulation of PTPRK in breast cancer cell lines was associated with increased cell proliferation, adhesion, and invasion." (PMID 30838170, 2019). "For example, decreased PTPRK expression was reported in association with poor prognosis of breast cancer." (PMID 30838170, 2019). "PTPRK is a phosphatase, and its decreased expression was observed in breast cancer and correlated with the disease progression." (PMID 41465532, 2025). "Several studies had reported lower levels of PTPRK transcripts in breast cancer, colon cancer, and rhabdoid tumors." (PMID 30838170, 2019). "It has been reported that decreased expression of PTPRK correlates with poor prognosis in breast cancer." (PMID 31027318, 2019). "Previous data from a breast cancer research demonstrated decreased PTPRK levels in the primary breast tumors." (PMID 30838170, 2019). "In breast cancer, PTPRK staining was stronger in tumor tissue compared to control, and patients with higher PTPRK mRNA levels presented higher overall and progression free survival." (PMID 31027318, 2019). "In vitro studies confirmed that the knockdown of PTPRK increased cell proliferation, adhesion, and invasion, suggesting it functions as a tumor suppressor in breast cancer." (PMID 30208623, 2018). "The expression of PTPRK mRNA transcript was reduced in the primary tumors harvested from breast cancer patients with metastatic tumors or who had succumbed to the disease." (PMID 30208623, 2018). "Breast cancer patients with decreased PTPRK transcript levels have shorter survival times and a higher probability of metastases." (PMID 28611294, 2017). "It has been reported that PTPRK expression is downregulated in many cancer types and cancer-cell lines including, melanoma, lung cancer, prostate cancer and breast cancer." (PMID 28611294, 2017). "Indeed, further studies have demonstrated, for example, that PTPRK negatively regulated adhesion and invasion in breast cancer cells." (PMID 30208623, 2018). "Moreover, PTPRK is proposed as an important regulator of EMT plasticity in breast cancer." (PMID 35335125, 2022). "Recent studies reported that drug-resistant breast cancer cells acquire EMT characteristics and have increased motility and invasion activities by suppression of CLDN3, CDH1, and PTPRK." (PMID 35335125, 2022). "Additionally, knockdown of PTPRK in MDA-MB-231 and MCF-7 breast cancer cell lines resulted in increased cell proliferation, adhesion and invasion." (PMID 31027318, 2019).
glioma (7 papers, 2013 to 2025). A benign or malignant brain and spinal cord tumor that arises from glial cells (astrocytes, oligodendrocytes, ependymal cells). "The loss of active PTPRK in gliomas was associated with a higher level of resistance to chemotherapy and reconstitution of wild-type PTPRK in malignant glioma-cell lines improved the effect of conventional therapeutics." (PMID 28611294, 2017). "We next evaluated the role of PTPRK and its variants in glioma invasion using matrigel invasion chambers." (PMID 23696788, 2013). "Further, we determined consequences of ectopic expression of PTPRK and its variants on diffusive characteristic of glioma cells with in vitro wound healing assay." (PMID 23696788, 2013). "The effect of these mutations on PTPRK anti-oncogenic function and their association with response to anti-glioma therapeutics, such as temozolomide and tyrosine kinase inhibitors, was subsequently analyzed using in vitro cell-based assays." (PMID 23696788, 2013). "Ectopic expression of PTPRK-wt in glioma cells showed significant reduction in the proliferation, migration and invasion rates compared to PTPRK variants possibly via negative regulation of EGFR and β-catenin signaling." (PMID 23696788, 2013). "Subsequent sequencing of the full length PTPRK transcripts revealed novel PTPRK gene deletion and missense mutations in numerous glioma biopsies." (PMID 23696788, 2013). "Our recent SNP array screening of glioma biopsies implicated PTPRK as an independent prognostic factor in malignant glioma." (PMID 23696788, 2013). "PTPRK induced inhibition of glioma migration and effect of its mutations were confirmed in U251-MG cell line." (PMID 23696788, 2013). "Mutation in the PTPRK gene correlated with chemoresistance in glioma." (PMID 41465532, 2025). "Mutation in PTPRK gene leads to increased chemotherapy resistance in glioma." (PMID 31027318, 2019). "The use of mapping arrays revealed that genetic alterations (gene deletion and missense mutations) of PTPRK could be found in glioma biopsies, and they disrupt PTPRK activity and post-translational regulation." (PMID 30208623, 2018). "We observed that the PTPRK locus undergoes allelic loss in glioma which may contribute to the cancer phenotype." (PMID 23696788, 2013). "The results demonstrate biological relevance of PTPRK loss in glioma pathogenesis." (PMID 23696788, 2013). "Future studies require further analysis of PTPRK variants in a larger group of glioma patients." (PMID 23696788, 2013). "In summary, our findings provide compelling evidence in support of tumor-suppressive properties of PTPRK and its prognostic significance in glioma along with discovery of several mutations leading to altered functionality of the PTPRK protein which subsequently affect therapeutics." (PMID 23696788, 2013). "However, PTPRK mutations abrogated tumor suppressive effects of wild-type PTPRK and altered sensitivity of glioma cells to chemotherapy." (PMID 23696788, 2013). "In glioma cells, PTPRK is involved in epidermal growth factor receptor (EGFR) and b-catenin dephosphorylation and loss of PTPRK activity results in increased EGFR and b-catenin phosphorylation." (PMID 31027318, 2019). "These genetic alterations influenced PTPRK dephosphorylation and adhesion properties and are responsible for major alterations in PTPRK mediated suppression of glioma cell migration, diffusion and invasion." (PMID 23696788, 2013). "Using mapping arrays to screen for genomic alterations in gliomas, we recently identified alterations of the protein tyrosine phosphatase receptor type kappa gene (PTPRK) that correlate to patient outcomes." (PMID 23696788, 2013). "Overall, our results clearly indicate that PTPRK expression in glioma cells improves clinical response to these anti-cancer drugs, in vitro." (PMID 23696788, 2013). "PTPRK induced chemosensitivity of glioma cells was further confirmed in U251-MG cell line and were consistent with findings in U87-MG cells." (PMID 23696788, 2013).
glioma (continued). "This current extension of our investigations into the role of PTPRK in malignant glioma illustrates its biological relevance as a negative regulator of glioma proliferation, migration and invasion." (PMID 23696788, 2013). "Initial analysis of PTPRK protein levels in human glioma biopsies confirmed that PTPRK protein is proteolytically processed into several fragments." (PMID 23696788, 2013). "These PTPRK alterations are very relevant to glioma biology as PTPRK can directly sense cell–cell contact and is a dephosphorylation regulator of tyrosine phosphorylation signaling, which is a major driving force behind tumor development and progression." (PMID 23696788, 2013). "Malignant glioma cells expressing PTPRK-wt proliferated at a significantly reduced rate, resulting in 80% difference in growth compared to mock cells (P = 0.0002)." (PMID 23696788, 2013). "The rationale is that infiltrative behavior of malignant glioma cells into surrounding brain parenchyma that makes current treatments less effective is highly dependent on PTPRK genetic status." (PMID 23696788, 2013). "In another study, U87-MG glioma cells transfected with wt-PTPRK were significantly more sensitive to temozolomide, erlotinib and gefitinib or combination of temozolomide with erlotinib or gefitinib than the same cells transfected with mutated, inactive form of PTPRK." (PMID 31027318, 2019). "PTPRK appears to be a negative regulator of adhesion, invasion, migration, and proliferation in various tumor types, including breast and colorectal cancers, gliomas, lymphoma, and melanoma cells." (PMID 26432421, 2015). "Furthermore, our results showed that limiting glioma infiltration and migration by expression of functional PTPRK results in an improved response to several anti-glioma agents." (PMID 23696788, 2013). "PTPRK-wt expression significantly reduced glioma cell invasiveness by 40% (P<0.001)." (PMID 23696788, 2013). "PTPRK alterations seem relevant to glioma biology as PTPRK is highly expressed in brain." (PMID 23696788, 2013). "Moreover, we discovered that the PTPRK genetic status can predict in vitro response to anti-glioma therapies such as temozolomide and several tyrosine kinase inhibitors." (PMID 23696788, 2013). "Based on previous studies, we hypothesized that PTPRK may regulate growth, invasion and migratory phenotype of glioma cells through tyrosine dephosphorylation of β-catenin and receptor tyrosine kinases such as EGFR." (PMID 23696788, 2013). "Screening of PTPRK substrates using commercially available “tyrosine phosphatase substrate sets” and subsequent validation of identified substrates in relation to their relevance in glioma biology is required for better understanding of PTPRK regulated molecular events." (PMID 23696788, 2013). "As hypothesized, these alterations in PTPRK phosphatase activity and post-translational modification altered the suppressive effects of PTPRK on glioma growth, migration and invasive phenotypes." (PMID 23696788, 2013). "Moreover, PTPRK mutations altered the inhibitory effect of wild type PTPRK on EGFR and β-catenin signaling pathways which correlate with observed alterations in PTPRK mediated suppressive effects on growth and migration of glioma cells." (PMID 23696788, 2013). "In our recent study, LOH at the PTPRK locus was observed in 23% of glioma patients." (PMID 23696788, 2013). "Interestingly, glioma patients with deleted or inactivated PTPRK have poor overall survival compared to those with normal PTPRK locus." (PMID 23696788, 2013). "In future, with data herein being confirmed using in vitro and in vivo models, PTPRK may be used as a therapeutic predictive marker for tyrosine kinase inhibitors and other anti-glioma agents." (PMID 23696788, 2013).
glioma (continued). "PTPRK was proved to be involved also in glioma progression since patients with deleted or inactivated PTPRK had poor overall survival when compared to those with normal PTPRK locus and restoration of wild-type PTPRK (wt-PTPRK) in glioma cell lines resulted in reduced cells growth and migration." (PMID 31027318, 2019). "However, it is as yet unclear if the maintenance of required PTPRK expression levels could serve as a sufficient “checkpoint” in the molecular events leading to glioma development and progression." (PMID 23696788, 2013). "Thus, re-expression of PTPRK and consequent intercellular homophilic interactions in glioma cells might induce contact inhibition of growth and thereby send downstream signals to reduce EGFR and β-catenin levels." (PMID 23696788, 2013). "In contrast, PTPRK overexpression was followed by higher sensitivity to cytotoxic drugs in acute lymphoblastic leukemia (ALL) cell lines and glioma cells." (PMID 33921897, 2021). "Since we observed a major role of PTPRK in checking glioma aggressiveness (proliferation, diffusion and invasion), and as malignant gliomas are characterized by a remarkably high chemo-resistance, we analyzed whether PTPRK status modulates the chemosensitivity of malignant glioma cells." (PMID 23696788, 2013). "Despite a potential key role of PTPRK in glioma biology, functional data related to PTPRK alterations in gliomagenesis are lacking." (PMID 23696788, 2013). "Reconstitution of wild-type PTPRK in malignant glioma cell lines suppressed cell growth and migration by inhibiting EGFR and β-catenin signaling and improved the effect of conventional therapies for glioma." (PMID 23696788, 2013). "Moreover, the physiological role of PTPRK as a putative tumor suppressor and its capacity to influence the malignant glioma phenotype has not been studied to date although PTPRK is highly expressed in the brain." (PMID 23696788, 2013). "Interestingly, PTPRK-wt expression reduced EGFR and β-catenin protein levels in glioma." (PMID 23696788, 2013). "Full length PTPRK (180-kDa) was not detectable in a majority of the analyzed glioma biopsies." (PMID 23696788, 2013). "As expected, using MTT cytotoxicity assay, we observed increased sensitivity of malignant glioma cells to anticancer drugs following expression of functionally active wild-type PTPRK and little or no significant change in sensitivity with abnormal PTPRK, compared to mock cells." (PMID 23696788, 2013).
celiac disease (6 papers, 2016 to 2024). An autoimmune genetic disorder with an unknown pattern of inheritance that primarily affects the digestive tract. "Compromised epithelial barrier integrity is also linked to inflammatory bowel disease susceptibility; therefore, PTPRK SNPs linked to celiac disease should be investigated." (PMID 30924770, 2019). "Fine-mapping data for coeliac disease localised the causal variants driving this association close to the 3’ UTR of PTPRK." (PMID 27438997, 2016). "Since epithelial barrier integrity and wound healing support responses to damage, and because PTPRK has been linked genetically to coeliac disease, we next sought to determine whether PTPRK is required for injury recovery in the colon." (PMID 38904097, 2024). "PTPRK has previously been found to be downregulated in coeliac disease colons, indicating a potential function in colon injury responses." (PMID 38904097, 2024). "There are 39 gene loci showing variation in Celiac Disease patients, at least four of which are known to play roles in cell–cell adhesion (LPP, C1orf106, PTPRK and PARD3), one piece of evidence suggesting a primary barrier defect may exist in Celiac Disease." (PMID 35328419, 2022). "We focused our investigations on Immunochip SNP rs13204742, yet dense genotyping in celiac disease and multiple sclerosis has revealed multiple independent signals at the THEMIS/PTPRK locus so further work will be required to refine the association signals within this region." (PMID 27438997, 2016). "Notably, an association between SNP rs802734 and coeliac disease has also been demonstrated, and subsequent investigations have shown that this SNP influences THEMIS, but not PTPRK, expression in treated coeliac disease patients." (PMID 27438997, 2016).